SNHG7 (small nucleolar RNA host gene 7)
Diseases named in the same sentence as SNHG7 in open-access papers (continued):
Sharing a sentence is not in itself a finding about the gene and the disease.
cardiac hypertrophy (2 papers, 2022 to 2025). "For instance, H19 and RMRP are involved in heart failure progression, while BDNF-AS is a cardiomyocyte damage-associated gene; SNHG7 is a cardiac hypertrophy regulator." (PMID 35415316, 2022). "Snhg7 induces ferroptosis (a form of iron-dependent cell death) and contributes to cardiac hypertrophy by interacting with T-box protein 5 (Tbx5), a critical TF for cardiac development and function." (PMID 39857701, 2025). "A recent study identified Snhg7, a novel lncRNA driven by SEs, as a key player in cardiac hypertrophy." (PMID 39857701, 2025). "Another lncRNA, namely SNHG7, has also emerged as a novel regulator for cardiac hypertrophy." (PMID 35415316, 2022). "SNHG7 was up-regulated in the in vitro ANT-treated samples as well as ANT-treated patients, while a study in neonatal rat cardiomyocytes revealed that the up-regulation of the SNHG7 genes can stabilize SDAD1 mRNA, and then facilitate cardiac hypertrophy." (PMID 35415316, 2022).
esophageal cancer (2 papers, 2019 to 2020). A primary or metastatic malignant neoplasm involving the esophagus. "In our research, we discovered that 3 lncRNAs from SNHG family (SNHG1, SNHG7, and SNHG12) were upregulated in ESCA (esophageal carcinoma) tissues based on Cancer RNA‐Seq Nexus analysis." (PMID 32239639, 2020).
liver cancer (2 papers, 2021 to 2022). An epithelial or non-epithelial malignant neoplasm that arises from the liver. "Overexpression of SNHG7 impeded NLRP3-dependent pyroptosis in liver cancer cells." (PMID 36387211, 2022). "In liver cancer, NLRP3-related pyroptosis pathway suppressed by SNHG7 through regulation of miR-34a/SIRT1 ceRNA axis." (PMID 34488540, 2021).
lung adenocarcinoma (2 papers, 2020 to 2025). A carcinoma that arises from the lung and is characterized by the presence of malignant glandular epithelial cells. "Elevated expression of SNHG7 is observed in docetaxel-resistant cells in lung adenocarcinoma with resistance to docetaxel." (PMID 41301542, 2025). "While SNHG7 exhibits context-dependent effects in lung adenocarcinoma, its downregulation inhibits the Wnt signaling pathway through miR-181/CBX7, yet exosome-derived SNHG7 exacerbates malignancy by modulating autophagy and immune suppression." (PMID 41301542, 2025). "To examine the relationship between lncRNA perturbators and lncRNA-perturbated mRNAs, we overexpressed lncRNA SNHG7 and TUG1 in the A549 lung adenocarcinoma cell line." (PMID 32846981, 2020). "Additionally, SNHG7 interacts with CUL4A to promote the ubiquitination and degradation of PTEN, thereby activating the PI3K/AKT pathway, inducing M2 macrophage polarization, and ultimately enhancing docetaxel resistance in lung adenocarcinoma cells." (PMID 41301542, 2025).
melanoma (2 papers, 2022 to 2024). A malignant, usually aggressive tumor composed of atypical, neoplastic melanocytes. "For example, the lncRNA SNHG7 (small nucleolar RNA host gene 7) promotes invasion in melanoma via the upregulation of SOX4, another master regulator of EMT." (PMID 35406721, 2022).
prostate adenocarcinoma (2 papers, 2022). "In addition, elevated SNHG7 associated with worse PFI in ACC, KIRP, LIHC, Prostate adenocarcinoma (PRAD) and UCS (p<0.05)." (PMID 34979987, 2022).
bladder urothelial carcinoma (1 paper, 2021). "It has revealed that SNHG7 upregulation was correlated with worse OS in COAD, bladder urothelial carcinoma (BLCA), LIHC (log-rank P<0.05), which partially confirmed our results in this meta-analysis." (PMID 34714775, 2021).
coronary artery disease (1 paper, 2023). "SNHG7 was downregulated in unstable plaques of patients with coronary artery disease, suggesting the potential role of its low expression in the regulation of coronary artery disease." (PMID 37109540, 2023).
lentivirus infection (1 paper, 2019). Virus diseases caused by the Lentivirus genus. "We also confirmed that SNHG7 was repressed by metformin and upregulated by lentivirus infection, and SNHG7 upregulation inhibited metformin-activated AMPK signaling." (PMID 30853913, 2019).
lupus erythematosus (1 paper, 2022). An autoimmune, connective tissue chronic inflammatory disorder affecting the skin, joints, kidneys, lungs, heart, and the peripheral blood cells. "Finally, gene set enrichment analysis showed that SNHG7 may affect lupus erythematosus and reactome cellular senescence, possibly influencing the prognosis of patients with COAD." (PMID 35747807, 2022).
myocardial infarction (1 paper, 2024). Gross necrosis of the myocardium, as a result of interruption of the blood supply to the area, as in coronary thrombosis. "Importantly, in the mice with myocardial infarction, the expression of small nuclear RNA host gene 7 (SNHG7) is facilitated and its depletion exerts a beneficial function in myocardial infarction." (PMID 39014478, 2024). "Besides, in mice myocardial infarction models, overexpressed SNHG7 is also detected, which contributes to cardiac fibroblasts apoptosis, fibrosis and inflammation." (PMID 39014478, 2024). "It is known that acute myocardial infarction is a subtype of ACS, thus, SNHG7 may be involved in ACS." (PMID 39014478, 2024).
nasopharyngeal carcinoma (1 paper, 2022). A carcinoma arising from the nasopharyngeal epithelium. "A recent study demonstrated that LncRNA SNHG7 bound with miR-514a-5p and negatively modulated miR-514a-5p expression, and miR-514a-5p deficiency restored the progression of nasopharyngeal carcinoma inhibited by the knockdown of SNHG7." (PMID 35135416, 2022).
Nephropathy (1 paper, 2023). A nonspecific term referring to disease or damage of the kidneys. "In contrast, Br-MSCs + EXO, EXOs, and Br-MSCs’ transplantation caused a significant (p < 0.001) downstream regulation of mir-34a, mTOR, and AKT expression, and upstream regulation in SNHG-7, AMPK, and ULK-1 expression, respectively, compared with nephropathy and CM-treated groups." (PMID 37631363, 2023).
osteoarthritis (1 paper, 2023). A noninflammatory degenerative joint disease occurring chiefly in older persons, characterized by degeneration of the articular cartilage, hypertrophy of bone at the margins and changes in the synovial membrane. "More strikingly, LncRNA small nucleolar RNA host gene 7 (SNHG7) played an important role in osteoarthritis apoptosis and autophagy via sponging miR-34a-5p." (PMID 37175724, 2023).
ovarian tumour (1 paper, 2020). "Importantly, SNHG7 expression was elevated in ovarian tumour tissues as measured by qRT‐PCR compared to control non‐cancerous tissues, indicating that SNHG7 is significantly up‐regulated during OC (P < .01)." (PMID 32420685, 2020). "SNHG7 expression was elevated in ovarian tumour tissues measured by qRT‐PCR." (PMID 32420685, 2020).
pituitary adenoma (1 paper, 2021). "Small nucleolar RNA host gene 7 (SNHG7) is among the oncogenic lncRNAs with progressive effects in multiple human cancers although a single study suggests tumor suppressor function for SNHG7 in pituitary adenoma." (PMID 35111760, 2021).
polycystic ovary syndrome (1 paper, 2022). A disorder that manifests as multiple cysts on the ovaries. "For example, miR-21 suppressed ovarian granulosa cell proliferation by targeting SNHG7 in premature ovarian failure with polycystic ovary syndrome." (PMID 35034562, 2022).
rectal cancer (1 paper, 2022). A primary or metastatic malignant neoplasm that affects the rectum. "LncRNAs can bind to miR-34a and disrupt the regulation of miRs and target genes, including GAPLINC and SNHG7, which may increase, migrate, and invade rectal cancer cells." (PMID 35654932, 2022).
cancer (49 papers, 2018 to 2025). A tumor composed of atypical neoplastic, often pleomorphic cells that invade other tissues. "Accumulating studies have demonstrated the association of SNHG7 with multiple human cancers via complicated mechanisms." (PMID 32982586, 2020). "The greatest increase in relative expression was observed for a cancer-associated lncRNA that may inhibit autophagy (Small Nucleolar RNA Host Gene 7 or SNHG7, PFDR ≤ 0.0041, mean logFC = 2.0)." (PMID 36271102, 2022). "Moreover, the violin plot showed that SNHG7 expression was also significantly associated with the clinical stage of human cancers (P < 0.05)." (PMID 34714775, 2021). "Hence, SNHG7 is regarded as a significant cancer-associated biomarker." (PMID 37916187, 2023). "An increase in the expression levels of SNHG7, ASMTL-AS1, and LINC02604 in cancer samples was significantly associated with a higher mortality rate among patients." (PMID 39028420, 2024). "Articles related to the SNHG7 as a prognostic biomarker for cancer patients, were comprehensive searched in several electronic databases." (PMID 34979987, 2022). "SNHG7 serves as an oncogene and contributes to cell biological functions in various cancers, which including apoptosis inhibition, cell proliferation, cell cycle arrest, invasion, migration, and vasculogenic mimicry." (PMID 34979987, 2022). "Recent studies have shown that SNHG7 promotes proliferation, migration and invasion of various cancers and inhibits tumor cell apoptosis." (PMID 35912250, 2022). "As previous research works reported, lncRNA SNHG7 has been widely reported in various cancers to promote M2 polarization, therefore enhancing drug resistance." (PMID 35237300, 2022). "In the present study, a qualitative meta-analysis was conducted to explore the prognostic effect of SNHG7 on cancer patients." (PMID 34979987, 2022). "Many clinical and fundamental studies suggested that increasing levels of SNHG7 have intimate terms with unfavorable prognosis and progression in cancer patients." (PMID 34979987, 2022). "One of the lncRNAs that have a notable impact on the cancer cell cycle and proliferation is the small nucleolar RNA host gene 7 (SNHG7) lncRNA." (PMID 36294743, 2022). "These evidences encouraged us to investigate the correlation between SNHG7 expression levels and cancer prognosis." (PMID 34979987, 2022). "In other words, using siRNA to downregulate SNHG7 expression in exosomes that promote drug resistance is conducive to maintaining or recovering the sensitivity of cancer cells to chemotherapy drugs." (PMID 36685535, 2022). "SNHG7 was significantly upregulated in four cancers and the elevated expression of SNHG7 predicted shorter OS in four cancers, worse DFS in five malignancies and worse PFI in five carcinomas based on the validation using the GEPIA on-line analysis tool." (PMID 34979987, 2022). "New evidence from clinical and fundamental researches suggests that SNHG7 is involved in the occurrence and development of carcinomas." (PMID 34979987, 2022). "New evidence from clinical and fundamental researches suggests that lncRNA SNHG7 is expressed in many tissues and involved in the occurrence and development of various carcinomas." (PMID 34979987, 2022). "A growing number of articles have shown how SNHG7 participated in running processes of molecular biological pathways in the occurrence and development of cancer." (PMID 34714775, 2021). "Our analysis showed that the up-regulated SNHG7 expression had a positive correlation with the worse overall survival in cancer patients." (PMID 34714775, 2021). "Xenograft animal studies confirm the oncogenic role of SNHG7 as tumor growth and metastasis of grafted cancer cells are promoted, whereas SNHG7 knockdown represses them." (PMID 35111760, 2021). "In vitro experiments frequently demonstrate a promoted malignant phenotype of cancer cells on SNHG7 overexpression, whereas its knockdown reverses tumor cell proliferation, migration, and invasion and enhances apoptosis." (PMID 35111760, 2021).
cancer (continued). "Excavation of TCGA dataset valuated that SNHG7 was upregulated in some cancers and predicted worse OS, which partially confirmed our results in this meta-analysis." (PMID 34714775, 2021). "SNHG7 was considered as a novel oncogenic lncRNA for its abnormal expression in various types of cancer." (PMID 34714775, 2021). "Through study of SNHG7 knockdown or overexpression in cancer cell lines, it is demonstrated that expression of this oncogenic lncRNA promotes malignant features of the cells in vitro." (PMID 35111760, 2021). "Playing a role in regulation of cellular processes, signaling pathways, transcription factors, and particularly via sponging miRNAs, SNHG7 is described as an oncogenic lncRNA with upregulation in various types of cancer cells." (PMID 35111760, 2021). "In this study, a meta-analysis was performed to evaluate the clinicopathologic and prognostic value of SNHG7 in cancers." (PMID 34714775, 2021). "In conclusion, regarding a considerable number of studies that reveal oncogenic role of SNHG7 in human cancers and its prognostic value, SNHG7 is suggested as a potential cancer biomarker for human malignancies." (PMID 35111760, 2021). "Enhanced glycolysis through upregulation of lactate dehydrogenase A (LDHA) in the tumor microenvironment is another finding on SNHG7 overexpression, which can help the cancer cell economy." (PMID 35111760, 2021). "The host gene 7 (SNHG7) of nucleolar RNA is a newly identified carcinogenic long non-coding RNA in cancer." (PMID 32528134, 2020). "In summary, this study indicated that SNHG7 contributed to the chemoresistance of BC and mediated chemoresistance and cancer stemness by sponging miR-34a." (PMID 33330080, 2020). "lncRNA SNHG7 (small nucleolar RNA host gene 7) has been demonstrated to participate in cell development and progression of many diseases, especially in cancers." (PMID 32066502, 2020). "LncRNA small nucleolar RNA host gene 7 (SNHG7) was identified as an important oncogene and played pre-eminent roles in several cancers." (PMID 31694052, 2019). "Already 24 h after transfection, the differentially expressed genes exhibited a notable bias towards downregulated genes, which is consistent with the idea that SNHG7 might be a miRNA regulator, as reported in cancer settings." (PMID 39054371, 2024). "Additionally, SNHG7 can function as a competing endogenous RNA (ceRNA) to promote cancer development." (PMID 37916187, 2023). "Given its important regulatory role in cancer biology, we wondered whether SNHG7 is involved in drug resistance to anlotinib (ATB) in CRC." (PMID 36691432, 2023). "In conclusion, the present analysis implicated that elevated SNHG7 is strongly associated with OS, tumor progression, LNM and DM in carcinomas, and may be served as a promising biomarker to guide therapy for various cancer patients." (PMID 34979987, 2022). "In addition, some studies have demonstrated that couple of lncRNAs, such as lincRNA-p21, LINC01106, small nucleolar RNA host gene 7, perform an increasingly vital role in carcinogeneses of human cancers through targeting miR-449a." (PMID 35212607, 2022). "Taken together, these results indicate that SNHG7 could be a novel prognostic biomarker for various cancers." (PMID 34979987, 2022). "SNHG7 was found to be highly expressed in 17 types of cancer, including COAD." (PMID 35747807, 2022). "Notably, SNHG1 and SNHG7 not only regulated many FA metabolism related-genes, but also mediated cancer cell ferroptosis." (PMID 36195833, 2022). "The present analysis suggests that elevated SNHG7 is significantly associated with unfavorable OS, tumor progression, LNM and DM in various carcinomas, and may be served as a promising biomarker to guide therapy for cancer patients." (PMID 34979987, 2022). "An overview to the oncogenic influences of SNHG7 in cell studies of different types of cancer." (PMID 35111760, 2021). "SNHG7 was commonly overexpressed in a variety of cancers as an oncogene." (PMID 34512753, 2021).
cancer (continued). "SNHG7 is an lncRNA with upregulation in cancer cells and tissues." (PMID 35111760, 2021). "In summary, we made conclusion that SNHG7 plays inconsistent roles in different cancer." (PMID 34714775, 2021). "Furthermore, a growing number of studies have explored the prognostic value of SNHG7 in various cancers, and suggested it can be exploited as a possible biomarker and therapeutic target for helping to improve diagnosis of cancer patients." (PMID 34714775, 2021). "Collectively, we believed that lncRNA SNHG7 was involved in the tumor development and progression, and may become a promising biomarker for prognosis in cancer patients." (PMID 34714775, 2021). "Thus, it is not surprising to see repressed apoptosis frequently reported on SNHG7 overexpression, which means steady growth of cancer cells." (PMID 35111760, 2021). "This further validates that SNHG7 is important in cancer development and proliferation." (PMID 32444795, 2020). "lncRNA SNHG7 was reported to as an oncogene in several cancers." (PMID 32066502, 2020). "Together, these findings suggest SNHG7 regulation is altered in tumours and that there may be a functional role for this lncRNA in cancer." (PMID 32420685, 2020). "Furthermore, SNHG7 may act as a competitive endogenous RNA (ceRNA) to aggravate the development of cancers." (PMID 34979987, 2022). "A handful of evidence on the acceleration of the cell cycle in response to SNHG7 overexpression or arrest in a phase under knockdown conditions suggests indirect enhancing influences of this lncRNA on cell proliferation and differentiation, which consequently, leads to cancer progression." (PMID 35111760, 2021). "Importantly, SNHG7 is demonstrated as a potential therapeutical target as it is identified in several studies to lead to enhanced chemoresistance to several anticancer agents such as Cisplatin, Trastuzumab, and Folfirinox in the cancer cells." (PMID 35111760, 2021). "The findings revealed a significant and substantial increase in the expression levels of SNHG7, ASMTL-AS1, and LINC02604 genes in cancer samples compared to normal samples." (PMID 39028420, 2024). "Among the 22 SNHG families, SNHG5, SNHG7, SNHG12, and SNHG16 are all known to promote cancer progression." (PMID 37189636, 2023). "To gain a comprehensive understanding of the role of SNHG7 in COAD, we first identified the differential expression of SNHG7 using publicly available pan-cancer data." (PMID 35747807, 2022). "SNHG7, which is a member of the SNHG family, is differentially expressed in various malignant tumors." (PMID 35747807, 2022). "Despite the inherent deficiencies, our study provides strong evidence that elevated lncRNA SNHG7 expression levels are prognostic for reduced OS, tumor progression, LYM and DM in cancer patients." (PMID 34979987, 2022). "It is worth highlighting that several lncRNAs play dual roles such as the lncRNA Small Nucleolar RNA Host Gene 7 (SNHG7), which has tumor suppressor or oncogenic activity depending on the kind of cancer." (PMID 34439196, 2021). "First, to confirm the regulatory pattern of SNHG12 in ESCC, we found that SNHG1, SNHG7, and SNHG12 were three upregulated lncRNAs in ESCC tissues through Cancer RNA‐Seq Nexus analysis." (PMID 32239639, 2020). "The carcinogenesis function of SNHG family in cancers has been widely reported, and the participation of SNHG1 and SNHG7 in ESCC has been researched, so we focused on SNHG12 in our research." (PMID 32239639, 2020). "The expression of SNHG7, as well as SDA1 domain containing 1 (SDAD1), a novel protein determined in human cancers, was raised in AngII-induced neonatal rat cardiac myocytes (NRCMs) hypertrophy." (PMID 31694052, 2019). "These included the cancer-related lncRNAs DLEU2, SNHG7, and LINC01554 (found in only polysomal and common fractions, respectively), the recently re-annotated lncRNA ENS00000269825 (common), the novel lncRNA ENS00000267882 (only total), and the lncRNA DANCR (common)." (PMID 38396700, 2024).